DNALI1 (dynein axonemal light intermediate chain 1)
Description:
Involved in sperm flagellum assembly.
Synonyms: P28; hp28; dJ423B22.5; SPGF83
Tractability: Small molecule: a structure with a bound ligand is known.
Gene: Protein-coding gene on chromosome 1 (37,556,919 to 37,566,857, forward strand). Ensembl gene ENSG00000163879.
Subcellular location: Cell projection, cilium; Cell projection, cilium, flagellum; Dynein axonemal particle; Cytoplasm
Subcellular location (Human Protein Atlas): End piece; Mid piece; Primary cilium; Principal piece; Cytokinetic bridge; Microtubules; Mitotic spindle; Nucleoplasm
Gene Ontology:
Molecular function: protein binding; dynein heavy chain binding
Biological process: sperm flagellum assembly
Cellular component: 9+2 motile cilium; axoneme; cilium; cytoplasm; motile cilium; sperm end piece; sperm flagellum; sperm midpiece; sperm principal piece; ciliary base; dynein axonemal particle; filopodium
Genetic constraint (gnomAD): Loss-of-function variants: 31 observed, 34.81 expected, observed/expected ratio (o/e) 0.89, 90% interval 0.67 to 1.2. The upper end of that interval is the gene's LOEUF score, 1.2, which puts it in group 5 of 6, group 1 being the genes least tolerant of losing a copy. Missense variants: 305 observed, 341.11 expected, observed/expected ratio (o/e) 0.89, 90% interval 0.81 to 0.98. Synonymous variants: 117 observed, 136.15 expected, observed/expected ratio (o/e) 0.86, 90% interval 0.74 to 1.
Homologues: Orthologues: chimpanzee DNALI1 (100% identical), macaque DNALI1 (99% identical), pig DNALI1 (99% identical), guinea pig DNALI1 (97% identical), rat Dnali1 (97% identical), mouse Dnali1 (96% identical), dog DNALI1 (94% identical), tropical clawed frog dnali1 (83% identical), zebrafish dnali1 (76% identical), rabbit DNALI1 (73% identical), Drosophila melanogaster Dnali1 (56% identical), Caenorhabditis elegans dyla-1 (37% identical).
Diseases named in the same sentence as DNALI1 in open-access papers:
DNALI1 is named in the same sentence as 24 diseases in open-access papers, as found by Europe PMC text mining. Sharing a sentence is not in itself a finding about the gene and the disease. The quoted sentences say what the papers report.
breast carcinoma (7 papers, 2012 to 2021). "Limited studies have reported that DNALI1 is down-regulated in breast cancer and negatively correlated with poor prognosis." (PMID 33763356, 2021). "DNALI1 is also supposed as a tumor suppressor gene because of its downregulated expression and positive correlation with overall survival in breast cancer." (PMID 30935420, 2019). "Among the other genes in the list, NAT1, DNALI1, SCUBE2, and TFF1 have been implicated in breast cancer." (PMID 23365541, 2012).
male infertility (6 papers, 2023 to 2025). The inability of the male to effect fertilization of an ovum after a specified period of unprotected intercourse. "Our results uncover a role of DNALI1 in sperm motility and male fertility in mice, and demonstrate that ICSI overcomes Dnali1-associated male infertility, thus providing guidance for the diagnosis and genetic counseling of DNALI1-associated human infertility." (PMID 37993789, 2023). "Collectively, these studies establish that ICSI is recommended as a suitable strategy for overcoming male infertility caused by DNALI1/Dnali1 deficiency." (PMID 37993789, 2023). "We next generated mice with a specific deficiency of DNALI1 in male germ cells, and observed a dramatic reduction of the sperm cells, which results in male infertility." (PMID 37083624, 2023). "Dnali1 deficiency induced damaged sperm motility, and caused complete male infertility." (PMID 37993789, 2023). "Despite this evidence indicating the potential significance of DNALI1 in modulating flagellogenesis, they sidestep the question of whether DNALI1 deficiency causes sperm dyskinesia and male infertility and, if so, what underlying mechanisms are behind it." (PMID 36792588, 2023). "It’s worth noting that both the reported Dnali1 cKO male mice and our Dnali1−/− mice display male infertility, damaged sperm motility, and disorganized fibrous sheath structure; these phenotypes recapitulate the reported phenotypes of the DNALI1-mutated infertile man." (PMID 37993789, 2023). "Finally, we show ICSI is an effective approach to overcome Dnali1-associated male infertility." (PMID 37993789, 2023). "Deficiency of DNAH12 leads to the failure of DNALI1 and DNAH1 recruitment to sperm flagella, resulting in abnormal sperm morphology characterized by compromised axoneme organization, causing male infertility." (PMID 40146200, 2025). "Overall, the sperm phenotypes of the Dnali1−/− mice were fully consistent with those of the DNALI1663_666del patient, thereby allowing us to declare that DNALI1 deficiency indeed caused male infertility with AZS." (PMID 36792588, 2023). "Mutations of DNAH12 cause male infertility by impairing DNAH1 and DNALI1 recruitment." (PMID 40568142, 2025). "To examine whether the male infertility caused by Dnali1 deficiency could be overcome, we performed intracytoplasmic sperm injection (ICSI) using the sperm from WT and Dnali1−/− male mice, and two-cell embryos were transferred into foster female mice." (PMID 37993789, 2023).
asthenozoospermia (4 papers, 2022 to 2023). "Previous studies identified two infertile men with asthenozoospermia harboring pathogenic mutations in DNALI1." (PMID 37993789, 2023). "This study does not recruit infertile men with asthenozoospermia to screen for potential mutations in human DNALI1 gene." (PMID 37993789, 2023).
infertile (4 papers, 2022 to 2023). "Herein, we detected a rare homozygous frameshift mutation in DNALI1 [c.663_666del (p.Glu221fs)] in a Chinese infertile AZS patient with consanguineous parents." (PMID 36792588, 2023). "Future studies screening infertile men for mutations in DNALI1 will provide more insights into the contribution of DNALI1 deficiency to human infertility." (PMID 37993789, 2023). "Male germ cell-specific Dnali1 knockout, Dnali1 conditional knockout (cKO) mice were infertile associated with significantly reduced sperm number and motility." (PMID 37083624, 2023). "Based on structural analysis, DNALI1 was found to be linked to the C-terminus of DNAH1, and infertile patients with DNAH1 mutations also presented DNALI1 defect in human beings." (PMID 36726469, 2022). "Our findings proposed that mutation in DNALI1 is novel genetic pathogenesis of asthenoteratozoospermia and this infertile defect can be overcome by ICSI for the first time." (PMID 36726469, 2022). "Recently, two studies reported that mutations in DNALI1 gene is associated with human infertility." (PMID 37993789, 2023). "In this study, the patient underwent two cycles of ICSI treatment and obtained a clinical pregnancy, which could provide a reference for other infertility due to DNALI1 deficiency." (PMID 36726469, 2022). "In addition, the consistent infertility phenotypes caused by DNALI1/Dnali1 deficiency, and the consistent ICSI outcomes between Dnali1-mutated mice and DNALI1-mutated men, are in line with the notion that the mutant mouse model is a useful reference for analyzing the genetics of human infertility." (PMID 37993789, 2023). "Les souris mâles mutées au niveau de Dnali1 présentaient une altération de la mobilité des spermatozoïdes et étaient complètement infertiles." (PMID 37993789, 2023).
ciliopathy (3 papers, 2022 to 2024). A genetic disorder of the cellular cilia or the cilia anchoring structures, the basal bodies, or of ciliary function. "We, therefore, examined whether other ciliopathy-associated phenotypes also exist in the Dnali1−/− mice." (PMID 36792588, 2023). "Finally, several factors related to ciliopathies such as DNALI1, DNAAF1, CCDC65, CCDC39, and LRRC34 were strongly reduced already at P17 (14–31% of wild-type level)." (PMID 36611846, 2022).
Huntington disease (2 papers, 2017 to 2022). Huntington disease (HD) is a rare neurodegenerative disorder of the central nervous system characterized by unwanted choreatic movements, behavioral and psychiatric disturbances and dementia. "The hub genes in gene set B were DNAI2, DNAI1, DNAH1, DNAH9 and DNALI1, all of which were enriched in Huntington’s disease." (PMID 36577966, 2022). "We also found many differentially expressed genes related to the Huntington disease (HD) pathway in both areas of the MPS II mouse model; among these, Bbc3, Bdnf, Crebbp, Dctn1, Dlg4, Gpx1, Grin1, Grin2b, Itpr1, and Pparg are up-regulated, while Dnaic2, Dnali1, Hap1, and Vdac2 are down-regulated." (PMID 28513549, 2017).
Hydrocephalus (2 papers, 2023). Hydrocephalus is an active distension of the ventricular system of the brain resulting from inadequate passage of CSF from its point of production within the cerebral ventricles to its point of absorption into the systemic circulation. "As we previously reported in the Drc1−/− mice, we identified hydrocephaly in nearly half of the Dnali1−/− mice, which may have resulted from ventricular ciliary dysfunction." (PMID 36792588, 2023). "In addition to reproductive phenotypes, hydrocephalus was also observed in some Dnali1−/− mice, indicating that DNALI1 may also function in motile cilia in the brain." (PMID 37993789, 2023).
primary ciliary dyskinesia (2 papers, 2022 to 2024). A rare, genetically heterogeneous, primarily respiratory disorder characterized by chronic upper and lower respiratory tract disease. "Among the testis-specific or highly expressed genes, also only the DNALI1 gene was mutated and has been associated with primary ciliary dyskinesia." (PMID 36726469, 2022).
alcohol abuse (1 paper, 2020). The use of alcoholic beverages to excess, either on individual occasions ("binge drinking") or as a regular practice. "In contrast, DNALI1, a hub gene in the cilium assembly enriched NAcdarkorange module, is under the genetic control of specific eQTL only in NAc but not in PFC, suggesting that changes to cilia organization due to alcohol abuse might be under different genetic control between the two brain regions." (PMID 33332381, 2020).
Azoospermia (1 paper, 2022). Absence of any measurable level of sperm,whereby spermatozoa cannot be observed even after centrifugation of the semen pellet. "In summary, our work demonstrates that genetic defects of DNALI1 severely impair sperm motility and contribute to the human azoospermia phenotype, for which ICSI treatment is an effective remedy for the first time." (PMID 36726469, 2022).
cognitive decline (1 paper, 2024). "Notably, both autophagic dysfunction and cognitive decline after TBI were alleviated by DNALI1 knockdown." (PMID 38348540, 2024).
Cognitive impairment (1 paper, 2024). Abnormal cognition is characterized by deficits in thinking, reasoning, or remembering. "Collectively, our results position DNALI1 as a critical protein implicated in cognitive impairment." (PMID 38348540, 2024). "Subsequent motor and cognitive performance assessments revealed that the knockdown of DNALI1 did not alter motor function (p < 0.95) but successfully rescued the cognitive impairment resulting from repeated mild closed head injury." (PMID 38348540, 2024).
dementia (1 paper, 2024). Loss of intellectual abilities interfering with an individual's social and occupational functions. "When comparing DNALI1 expression at different durations of loss of consciousness, we observed a significant difference between the “clinical dementia” and “non‐demented” groups, particularly when the duration of loss of consciousness exceeded 10 min (p = 0.047)." (PMID 38348540, 2024). "The DNALI1 gene is systematically screened through analyses of Aging, Dementia, and TBI studies, confirming its elevated expression both in vitro and in vivo." (PMID 38348540, 2024). "Furthermore, the expression of DNALI1 in TBI participants exhibited great predictive ability for dementia, which was even better than that of the Braak stage score (AUC = 0.81)." (PMID 38348540, 2024). "Notably, IFT protein 46 (IFT46), a component of the IFT complex, was significantly increased in participants with “clinical dementia” (p = 0.020), accompanied by a significant positive correlation with DNALI1 (r = 0.46, p = 0.0019)." (PMID 38348540, 2024). "Indeed, DNALI1 expression was significantly elevated in the “clinical dementia” group (TBI diagnosis and dementia pathology) (p = 0.0067)." (PMID 38348540, 2024).
malaria (1 paper, 2021). Malaria is a serious and sometimes fatal disease caused by a parasite that commonly infects a certain type of mosquito which feeds on humans. "The severe malaria K-TSPs model identified ten gene pairs capable of differentiating severe from non-severe malaria including: SLC38A2-SCML1, SLC25A40-MAP2K7, DNALI1-AGPAT3, LIFR-TBCD, STK17B-ORC2, SF3B1-USP48, ZNF148-ZCCHC2, CBX5-CHAF1A, CNOT7-PLXNA2, and CREM-IDH1." (PMID 34746025, 2021).
respiratory infections (1 paper, 2024). "Defects of those proteins cause a stiff, rapid, and flickery ciliary beating pattern, recurrent respiratory infections, axonemal disorganization, and abnormal assembly of GAS8, CCDC39, and DNALI1." (PMID 39056782, 2024).
carcinoma (1 paper, 2023). A malignant tumor arising from epithelial cells. "This study found that DNALI1 (p-value: 0.0000148), a flagellar protein, is overexpressed in BC, which has not been reported previously for any other carcinoma." (PMID 37900178, 2023).
neurodegenerative disease (1 paper, 2024). A disorder of the central nervous system characterized by gradual and progressive loss of neural tissue and neurologic function. "The ability of DNALI1 to regulate cell death pathways may have further implications for neurodegenerative diseases and other conditions where cell death is implicated." (PMID 38348540, 2024).
tumor (1 paper, 2021). "DNALI1 is widely expressed in the human testis, ovaries and other tissues, but the functions of DNALI1 in physiological processes and tumor development remain unclear." (PMID 33763356, 2021).
DNALI1 also shares sentences with these, for which no sentence is quoted: asthma (1 paper); bovine tuberculosis (1); brain diseases (1); head injury (1); invasive breast carcinoma (1); Neurodegeneration (1).